RNU6-1298P (RNA, U6 small nuclear 1298, pseudogene)
Gene: Small nuclear RNA gene on chromosome 4 (88,226,729 to 88,226,829, forward strand). Ensembl gene ENSG00000199326.
Homologues: Orthologues: chimpanzee U6 (99% identical), macaque U6 (87% identical), dog U6 (71% identical), mouse Gm23229 (67% identical). Paralogues in human: RNU6-1060P (87% identical), RNU6-116P (87% identical), RNU6-11P (87% identical), RNU6-37P (87% identical), RNU6-15P (86% identical), RNU6-24P (86% identical), RNU6-33P (86% identical), RNU6-34P (86% identical), RNU6-371P (86% identical), RNU6-1 (85% identical), RNU6-1175P (85% identical), RNU6-12P (85% identical), and 1286 more.